ZAP70 (zeta chain of T cell receptor associated protein kinase 70)
Diseases named in the same sentence as ZAP70 in open-access papers (continued):
Sharing a sentence is not in itself a finding about the gene and the disease.
Immunodeficiency (continued). "Down-regulation of ZAP70 leads to immunodeficiency, with particular reference to T-lymphocyte-mediated immunity, which is often dysfunctional in AD." (PMID 37056359, 2023). "As the immunophenotype of the two patients is characteristic of ZAP-70 immunodeficiency, the ZAP-70 gene was sequenced." (PMID 37313400, 2023). "Considering the importance of ZAP-70 in T cell and NK cell activation, great effort has been put to target ZAP-70 in order to control diseases derived from abnormal T or NK cell activation, such as immune disorders and autoimmune diseases." (PMID 33194762, 2020). "An important clue to underlying immunodeficiency in both these cases were reduced percentages of naïve Th/Tc which was evaluated in 4 cases of MHC class II deficiency and 1 case of ZAP70 deficiency." (PMID 30778343, 2019). "Reduced ZAP70 levels result in immunodeficiency, a condition often impaired in AD." (PMID 39766348, 2024). "Complete inhibition of ZAP70 may ameliorate T cell-driven autoimmunity at the expense of immunodeficiency, whereas partial inhibition of ZAP70 may exacerbate dysregulation of self-tolerance." (PMID 39041034, 2024). "Mutations in the ZAP70 gene cause a combined immunodeficiency characterized by low or absent CD8+ T cells and nonfunctional CD4+ T cells." (PMID 37313400, 2023). "Alterations in both the expression and function of the non-receptor tyrosine kinase Zap70 are associated with numerous human diseases including immunodeficiency, autoimmunity, and leukemia." (PMID 36078131, 2022). "Since the induction of GIA is most efficient in 4-5-month-old female mice, and ZAP-70−/− mice usually do not live that long, when kept under conventional conditions (own observation) due to their severe combined immunodeficiency; we performed our experiments with ZAP-70+/− mice." (PMID 31137740, 2019). "ZAP70 deficiency is associated with Immunodeficiency 48 that is a form of severe immunodeficiency characterized by a selective absence of CD8+ T cells." (PMID 31495056, 2019). "This section describes PID with autoimmunity including monogenetic diseases of the immune system affecting self-tolerance by thymic impairment (e.g., APECED) and/or other T-lymphocyte function deficiencies (ZAP70), syndromic diseases (JAK1 GOF) or metabolic diseases (Prolidase deficiency)." (PMID 31799221, 2019). "Recently, new Zap70 mutations, which do not result in immunodeficiency but rather in severe autoimmunity, have been described." (PMID 28415650, 2017). "Also, our results demonstrate that CIP2A is downstream of Zap70 activity during T-cell activation, which is interesting considering the role for Zap70 in human immune diseases." (PMID 27100879, 2016). "CD38+ B cells, exhibiting elevated levels of ZAP-70 and heightened protein tyrosine phosphorylation, are associated with increased production of pro-inflammatory cytokines and suppression of CD4+ T cell proliferation, thus contributing to the pathogenesis of immune disorders." (PMID 39044820, 2024). "A non-palmitoylable C564R Zap70 mutant, which has been reported in a patient suffering from immunodeficiency, is incapable of propagating TCR signaling and activating T cells." (PMID 36078131, 2022). "MHC Class II defect and defects in STIM1, DOCK2, SP110, ZAP70, and STK4 genes are categorized as combined immunodeficiencies as per the 2019 International Union of Immunological Societies Expert Committee classification of human inborn errors of immunity (IEI)." (PMID 33628209, 2020). "This limited data shows that ZAP-70+/− mice do not suffer in such severe immunodeficiency, as their homozygous counterparts, however, for the fine details of this aspect of the ZAP-70 heterozygous mice should be investigated more thoroughly." (PMID 31137740, 2019).
Immunodeficiency (continued). "In these heterozygous knockout animals, the immunodeficiency is not as pronounced as in ZAP-70−/− mice, as they have αβ T cells in their peripheral lymphoid organs; however, at significantly decreased numbers, with slightly increased B cell numbers." (PMID 31137740, 2019). "The function deletion of the ZAP70 tyrosine kinase in humans can lead to a serious immunodeficiency, characterized by non-functional CD4+ T cells and lacking mature CD8+ T cells." (PMID 30497506, 2018). "Notably, both R170C and R192W mutations negatively impacted the binding of ZAP-70 to the TCR ζ-chain, resulting in a complete absence in TCR-induced proliferation (this study and) and all patients presented with immunodeficiency and autoimmunity, in the absence of activating mutations." (PMID 37313400, 2023).
Autoimmunity (24 papers, 2013 to 2026). The occurrence of an immune reaction against the organism's own cells or tissues. "To model this chronic manifestation, we infected autoimmunity-prone SKG mice containing a mutation in the T cell adaptor ZAP-70 with Brucella species." (PMID 40366144, 2025). "Named for their discoverer (Shimon Sakaguchi), SKG mice bear a spontaneous mutation in the T cell receptor signaling adaptor ZAP-70 (W163C) that generates an autoimmunity-prone T cell repertoire." (PMID 40366144, 2025). "The SKG arthritis model was developed using a point mutation in the gene coding for ZAP-70, affecting TcR signaling and eventually leading to an effect upon thymic selection of T cells and, subsequently, autoimmunity." (PMID 40493163, 2025). "When comparing the clinical phenotype with other CID due to TCR signaling defects, LAT and ZAP70 deficiency present with the strongest tendency towards autoimmunity." (PMID 38112969, 2023). "Taken together, our work highlights how the R360P mutation contributed to human autoimmunity via impaired autoinhibition of ZAP70 regulation." (PMID 34923645, 2022). "In contrast, polymorphisms in the ZAP70 coding region or 3’-UTR have conversely been associated with autoimmune disorders including psoriasis and type 1 diabetes (rs17695937), inflammatory bowel disease (IBD, rs13420683), and RA (rs2278699)." (PMID 34012443, 2021). "Furthermore, reduced ZAP70 phosphorylation emerged as a hallmark of T cell exhaustion in sepsis, echoing findings in cancer and autoimmunity where defective TCR signaling contributes to immunoparalysis." (PMID 41306770, 2025). "Having demonstrated that the direction of effect for the ZAP70 T155M risk variant is a partial loss of function, targeting ZAP70 kinase activity with inhibitors to treat autoimmunity could come with unanticipated consequences." (PMID 39041034, 2024). "Additional complex ZAP70 genotypes associated with autoimmunity have been discovered." (PMID 39041034, 2024). "Thus, the ZAP70 T155M missense variant associated with autoimmunity impairs TCR signaling strength through an incomplete loss of function." (PMID 39041034, 2024). "Taken collectively, human genetics evidence suggests ZAP70 function must be optimized within a narrow range such that partially impaired activity or enhanced activity elicits autoimmunity." (PMID 39041034, 2024). "By dissecting the similarities and differences among mouse models of patient disease or mutations in ZAP70 that affect TCR signaling strength, we have gained insights into how perturbed ZAP70 function can lead to autoimmunity." (PMID 34923645, 2022). "That open conformation is detrimental to protein stability is also supported by reduced Zap70 expression in mice expressing YYAA mutated Zap70 leading to impaired TCR signaling and susceptibility to autoimmunity." (PMID 35860252, 2022). "Because of its indispensible role for TCR activation, deficiency, or aberrantly high expression of ZAP-70 in T cells expectedly result in immune deficiency [ZAP-70-related severe combined immunodeficiency syndromes (SCID)] and autoimmunity, respectively." (PMID 33194762, 2020). "Because of our work and that of others on ZAP70, it is likely that perturbations in other molecules affecting TCR signaling strength will be identified that also overcome tolerance mechanisms and cause autoimmunity." (PMID 34923645, 2022). "However, mouse models (eg, SKG mouse model) can provide additional insight into the importance of ZAP70 function for immune cell development, T cell repertoire selection, and the propensity for autoimmunity in Zap70 murine mutants." (PMID 34923645, 2022). "Considering that each Zap70 mutant we have studied may abrogate a specific function or regulation of ZAP70, it is likely that other mutations that disturb TCR signaling thresholds may influence tolerance mechanisms and cause autoimmunity." (PMID 34923645, 2022).
Autoimmunity (continued). "Previously, the role of ZAP-70 in the development of autoimmunity was clearly demonstrated by a well-established spontaneous murine model of arthritis, the SKG mice, where a spontaneous point mutation of the ZAP-70 coding gene results in the development of autoimmune arthritis." (PMID 31137740, 2019). "Whether the level of Rasal1 inhibition of ZAP-70 is sufficient to elicit effects on thymic differentiation is unclear; however, it may help protect against excess inflammation or autoimmunity and influence T-cell responses to antigens of varying affinities." (PMID 31641113, 2019). "In ZAP70-deficient patients, circulating T cells are under inadequate supervision, no longer differentiate into TH2 T cells, are short of inhibitory growth controls, and show decreased apoptosis, finally developing into inflammation and autoimmunity." (PMID 30497506, 2018). "Notably, ZAP70‐deficient mice, as well as LAT‐mutated mice (the latter discussed in more detail later in this review), reveal a causal link between impaired TCR signaling associated with immune dysregulation and autoimmunity." (PMID 34923645, 2022). "Studies from these Zap70 mutants demonstrated that impaired TCR signaling and thymic selection can produce a potentially autoreactive repertoire of TCRs, and revealed a signaling threshold below which autoimmunity develops." (PMID 34923645, 2022). "If Zap70 bound to phospho-CD3 is not phosphorylated it may act as a dominant negative, while undesired phosphorylation leading to its activation may result in autoimmunity due to increased sensitivity of TCR to self-ligands." (PMID 35860252, 2022).
Arthritis (22 papers, 2011 to 2025). Inflammation of a joint. "We also tested the effect of the anti-cit-OPN antibodies using mannan-induced arthritis in ZAP70-mutated SKG mice, which developed T cell-mediated autoimmune arthritis." (PMID 36804906, 2023). "SKG mice, harbouring the Zap70 W163C mutation, increase autoreactive Th17 cells intrinsically, and in a conventional environment, they exhibit spontaneous arthritis with fungal factors." (PMID 35879738, 2022). "The SKG mouse arthritis model, identified by Sakaguchi and associates, has a mutation in the ZAP70 signaling molecule that was caused by a spontaneous event." (PMID 34478449, 2021). "A third mouse model; the SKG model [a missense mutation in Zap70 resulting in spontaneous arthritis] has demonstrated induction of arthritis following inoculation of SKG mice with the gut microbiome of early RA patients." (PMID 33134291, 2020). "A key molecule in T cell activation is ZAP-70, therefore we aimed to investigate the effects of partial ZAP-70 deficiency on the pathogenesis of recombinant human G1(rhG1)-induced arthritis (GIA), a well-established mouse model of RA." (PMID 31137740, 2019). "SKG mice (BALB/c mice that harbor the W163C point mutation in zeta-chain-associated protein kinase 70 [i.e., ZAP-70]) were housed under arthritis-resistant, specific pathogen–free conditions." (PMID 26286534, 2015). "The SKG ZAP-70 mutation causes inadequate T cell receptor signaling, leading to disturbances in the T cell selection process, enabling the release of autoreactive T cells into the periphery, contributing to the pathogenesis of arthritis." (PMID 31137740, 2019). "ZAP-70+/− mice developed a less severe arthritis, as shown by both clinical picture and in vitro parameters (decreased T cell proliferation, cytokine and autoantibody production)." (PMID 31137740, 2019). "Based on these complex changes we conclude that the decreased level of the ZAP-70 in T cells shifts the balance between activation and apoptosis to the latter side which corresponds to the milder arthritis observed." (PMID 31137740, 2019). "The development of arthritis in SKG mice, which carry a mutation in the T-cell receptor component ZAP70, is suppressed by the deficiency of C5aR7." (PMID 26404464, 2015). "Abnormal ZAP70 could impaired TCR signal transduction in SKG mice and transgenic expression of the normal human ZAP70 gene in SKG mice could rescue the SKG arthritis, which emphasizes the critical function of ZAP70." (PMID 34986893, 2022). "These Zap70 mutations were sufficient to drive rheumatoid factor (RF) production in BALB/c mice challenged with zymosan but did not produce frank arthritis in response to identical environmental challenges that produced arthritis in the SKG line." (PMID 34923645, 2022). "Interesting results were provided by studies on the mouse model of arthritis and enteritis—SKG model, in which the carrier of the ZAP70 mutation is associated with disturbances in the signal pathway mediated by the prescription TCR (T-Cell Antigen Receptors), IL-23/IL-17." (PMID 33924414, 2021). "As the result of the ZAP-70 gene mutation in T cells, arthritis occurs spontaneously without LA, while the cellular source of IL-6 in SKG appears to be macrophages which can be affected by the PAMPs released from oral and gut microbiome of the mice." (PMID 33076980, 2020). "In SKG mice, arthritis development is attributed to a missense mutation in the TCR signaling adaptor molecule ZAP70, leading to a defective negative selection in the thymus and the release of autoreactive T cells." (PMID 30837986, 2019). "Here, we successfully induced arthritis in ZAP-70+/− mice, by the end of the experiment the incidence was similar to that of BALB/c mice, although the severity of articular inflammation was reduced based on clinical scores, supported by in vivo imaging, as well." (PMID 31137740, 2019).
Arthritis (continued). "Furthermore, we demonstrated that the IFN-γ induced by iNKT cell activation protected from severe arthritis in ZAP70 mutant mice, although the representation of potentially protective NKT1 cells diminished in the ankles as disease progressed." (PMID 29980684, 2018). "Notably, naïve SKG mice, which are zeta-chain-associated protein kinase 70 (Zap70) gene point mutation arthritis-prone mice, do not develop arthritis under GF conditions." (PMID 34576825, 2021). "Arthritis was induced in BALB/c and ZAP-70+/− heterozygous mice." (PMID 31137740, 2019). "Similarly, a spontaneously arising point mutation of ZAP70 in SKG mice led to a partial loss of function and impaired negative selection of autoreactive T cells resulting in arthritis." (PMID 39041034, 2024). "We did not see any differences in the incidence of arthritis when we compared the ZAP-70+/−- and ZAP-70+/+ groups, apart from some insignificant variations during the immunization period, both groups reached 100% incidence one week after the third immunization." (PMID 31137740, 2019).
severe combined immunodeficiency (21 papers, 2008 to 2026). Severe combined immunodeficiency (SCID) comprises a group of rare monogenic primary immunodeficiency disorders characterized by a lack of functional peripheral T lymphocytes resulting in early-onset severe respiratory infections and failure to thrive. "PURPOSE: Zeta-chain-associated protein kinase 70 (ZAP-70) deficiency, a rare form of combined immunodeficiency (CID), is caused by homozygous or compound heterozygous variants in the ZAP70 gene." (PMID 41790376, 2026). "ZAP70 deficiency is a rare form of combined immunodeficiency that can predispose individuals to infections and, in some cases, malignancies, such as leukemia and lymphoma." (PMID 40901120, 2025). "A C564R mutation in the C-terminal part of the kinase domain of Zap70 has been found to be associated with severe combined immunodeficiency in an 11-month-old female patient." (PMID 36078131, 2022). "A substitution of ZAP-70 cysteine in position 564 to arginine was associated with a case of severe combined immunodeficiency in a human patient, however, the molecular mechanism underlying this inborn error of immunity remained unresolved." (PMID 33482200, 2021). "A homozygous cysteine mutation (c.1690T>C; p.C564R) of ZAP-70 gene was reported to be associated with severe combined immunodeficiency in a human patient." (PMID 33482200, 2021). "ZAP70 deficiency results in a clinical picture of (severe) combined immunodeficiency (S)CID with abnormal T-cell receptor signaling and abnormal maturation and function of thymocytes." (PMID 31799221, 2019). "We assessed the proof of concept of this approach by correcting ZAP-70 deficient severe combined immunodeficiency (SCID) in mice." (PMID 18446234, 2008). "The loss of ZAP-70 function causes severe combined immunodeficiency (SCID)." (PMID 40005847, 2025). "Furthermore, recessive and compound heterozygous mutations in ZAP70 cause human severe combined immunodeficiency." (PMID 21980439, 2011). "Similarly, the missense mutation P80Q in Zap70 causes severe combined immunodeficiency (SCID) by reducing the stability of the Zap70 SH2 domain associated with rapid degradation of the protein." (PMID 19926274, 2009). "He received a diagnosis of severe combined immunodeficiency (SCID) with heterozygous mutations in the ZAP70 gene, which is a rare autosomal recessive form of SCID caused by abnormal T-cell receptor signaling." (PMID 36074738, 2022). "Inactivating mutations of ZAP–70 cause selective T cell deficiency in humans, which in turn leads to conditions such as severe combined immunodeficiency (SCID) and persistent infections." (PMID 26473606, 2015). "Classically, ZAP70-related combined immunodeficiency is characterized by normal CD3+ counts, normal or elevated CD4+T cells, and markedly reduced or absent CD8+ T-cells (0–2% of total T cells)." (PMID 40901120, 2025). "Loss of Zap70 in humans leads to Severe Combined Immunodeficiency (SCID) characterized by the absence of CD8 T cells and the presence of non-functional CD4 T cells." (PMID 24596147, 2014). "Its importance has been demonstrated by the observation that Zap70-deficiency in humans results in a Severe Combined Immunodeficiency (SCID) characterized by the absence of CD8+ T cells and in a defective activation of the CD4+ T-cell compartment." (PMID 28415650, 2017). "Mutations in genes that affect the development or function of T and B cells [DCLRE1C(ARTEMIS), ZAP70, RAG1/2, IL2RG, ILRA7, LIG4, JAK3, ADA] can result in intestinal inflammation along with recurrent infections from severe combined immunodeficiency (SCID)." (PMID 34122435, 2021).